NCAPH (non-SMC condensin I complex subunit H)
Diseases named in the same sentence as NCAPH in open-access papers (continued):
Sharing a sentence is not in itself a finding about the gene and the disease.
glioma (2 papers, 2025). A benign or malignant brain and spinal cord tumor that arises from glial cells (astrocytes, oligodendrocytes, ependymal cells). "Subsequently, we established gain-of-function and loss-of-function cell lines and identified that NCAPH promoted glioma cell proliferation, migration, invasion, and epithelial–mesenchymal transition (EMT) progression." (PMID 38587786, 2025). "In this study, we found the expression of NCAPH was upregulated in gliomas by bioinformatics analysis and was associated with poor prognosis." (PMID 38587786, 2025). "NCAPH is closely associated with poor prognosis of glioma patients." (PMID 38587786, 2025). "Our study found that NCAPH is highly expressed in gliomas and associated with poor prognosis." (PMID 38587786, 2025). "Thus, NCAPH can serve as a novel diagnostic marker for glioma progression and a potential therapeutic target in the future." (PMID 38587786, 2025). "Subsequently, an examination was conducted to evaluate the influence of NCAPH expression levels on the prognostic outcomes of primary and recurrent glioma patients using data from CGGA." (PMID 41210692, 2025). "The expression of NCAPH and potential mechanism regulating progression of glioma was verified by bioinformatics analysis." (PMID 38587786, 2025). "The findings revealed that overexpression of NCAPH effectively increased the invasive of glioma cells in comparison to the control group." (PMID 38587786, 2025). "In conclusion, the expression of NCAPH is significantly upregulated in glioma, and higher NCAPH correlates with characters of undesirable prognosis like WHO grade, IDH wild-type, and non-1p/19q codeletion." (PMID 38587786, 2025). "NCAPH correlated with DNA damage repair ability of glioma cells and facilitated the proliferation, invasion, and migration of glioma cells by promoting the PI3K/AKT signaling pathway." (PMID 38587786, 2025). "Results of IHC also indicated the expression of NCAPH protein in glioma tissue was significantly higher than that in normal brain tissues." (PMID 38587786, 2025). "At present, there are few studies on NCAPH in low-grade gliomas, and few studies on tumor immunotherapy and the selection of immunotherapy targets." (PMID 41210692, 2025). "This study identifies the important pro-tumor role of NCAPH in glioma and suggests that NCAPH is a potential therapeutic target." (PMID 38587786, 2025). "Functionally, upregulated NCAPH promotes the malignant hallmarks of glioma cells in vivo and in vitro." (PMID 38587786, 2025). "In contrast, we have verified the expression of NCAPH in different grades of gliomas, and our study is more comprehensive." (PMID 41210692, 2025). "The results of flow cytometry identified that when NCAPH was down-regulated, the apoptosis of glioma cells increased and they were arrested in G1 phase." (PMID 38587786, 2025). "As the potential role of NCAPH in glioma is unclear, we decided to conduct an in-depth exploration about the function of NCAPH in glioma." (PMID 38587786, 2025). "The results demonstrated migration ability of glioma cells was enhanced when NCAPH expression was upregulated, while the mobility reduced in NCAPH knockdown glioma cells." (PMID 38587786, 2025). "Enrichment analysis, flow cytometry, and correlation analysis revealed NCAPH promoted cell cycle of glioma cells from G1 to S phase, inhibited apoptosis, and was highly correlated with DNA damage repair genes." (PMID 38587786, 2025). "Mechanistically, NCAPH regulated the malignant progression of glioma cells through the PI3K/AKT signaling." (PMID 38587786, 2025). "In conclusion, our study reveals the correlation between NCAPH and the molecular and clinical characterization in glioma." (PMID 38587786, 2025). "Our study is the first to demonstrate NCAPH promotes malignant hallmarks of glioma." (PMID 38587786, 2025).
glioma (continued). "Based on the results of flow cytometry, we speculated that NCAPH could regulate the proliferation of glioma cells and CCK-8 assay and Colony-formation assay were performed." (PMID 38587786, 2025). "Importantly, overexpression of PIK3CA in glioma cells rescued knockdown NCAPH mediated proliferation, migration, invasion, and EMT processes." (PMID 38587786, 2025). "Based on above findings, NCAPH may play a role in the immune microenvironment of glioma by regulating Th2 cells." (PMID 38587786, 2025). "Glioma patients with high expression of NCAPH had an undesirable prognosis." (PMID 38587786, 2025). "In correlation analysis, NCAPH was positively correlated with DNA damage repair genes suggesting that decreased NCAPH may induce DNA damage in glioma cells." (PMID 38587786, 2025). "After adjusting other parameters in multivariate Cox regression analysis such as patient age, tumor grade, IDH status, and 1p/19q status, the results manifested NCAPH might play a predictor in glioma." (PMID 38587786, 2025). "In vivo experiments further demonstrated NCAPH promotes progression of glioma." (PMID 38587786, 2025). "It suggested upregulated NCAPH induced immune infiltration in glioma." (PMID 38587786, 2025). "Firstly, the downstream targets of NCAPH in glioma have only been briefly analyzed, and the more specific mechanism of NCAPH in regulating PI3K/AKT pathway is still unknown." (PMID 38587786, 2025). "To elucidate whether NCAPH regulates the migration and invasion of glioma cells via EMT process, we then investigated the expression of EMT-related proteins by WB." (PMID 38587786, 2025). "Furthermore, our drug sensitivity analysis showed that LGG patients with high NCAPH expression were particularly responsive to temozolomide, a chemotherapy drug commonly used in glioma treatment." (PMID 41210692, 2025). "The results of CCK-8 experiment and Colony-formation assay revealed that the upregulated NCAPH could promote the proliferation of glioma cells." (PMID 38587786, 2025). "According to enrichment analysis results that NCAPH might regulate cell cycle, DNA replication, and tumorigenesis in glioma, we take further experiments to confirm the function of NCAPH." (PMID 38587786, 2025). "Finally, the tumor-promoting effect of NCAPH in vivo was further verified by constructing a glioma nude mouse model." (PMID 38587786, 2025). "Series of experiments were taken to uncover the function of NCAPH in glioma." (PMID 38587786, 2025). "In addition, Transwell assay and Cell wound healing assay manifested that the overexpression of NCAPH could enhance the migration and invasion ability of glioma cells." (PMID 38587786, 2025). "The pathway that NCAPH may regulate in glioma remains unknown." (PMID 38587786, 2025). "Collectively, NCAPH may regulate tumorigenesis, cell cycle, and DNA replication in glioma." (PMID 38587786, 2025). "Apart from these, WB also identified despite knockdown of NCAPH, overexpression of PIK3CA decreased E-Ca expression along with increase in the Snail, vimentin, and N-Ca expression in glioma cells." (PMID 38587786, 2025). "However, the function of NCAPH in glioma remains unclear previously." (PMID 38587786, 2025). "The findings indicated that individuals with elevated NCAPH expression levels, particularly those diagnosed with WHO grade III glioma, exhibited unfavorable prognoses in both primary and recurrent cases." (PMID 41210692, 2025). "We firstly identified NCAPH promotes the proliferation, migration, invasion, and EMT process of glioma cells via PI3K/AKT pathway, and NCAPH is positively correlated with DNA damage repair in glioma cells." (PMID 38587786, 2025). "In summary, our study has conducted a more thorough and detailed exploration of the expression of NCAPH in gliomas, especially in low-grade gliomas, as well as its impact on the prognosis of LGG patients, and the influence of NCAPH expression on tumor proliferation and invasion." (PMID 41210692, 2025).
glioma (continued). "The expression of NCAPH increased significantly in glioma tissues and correlated with WHO grade, IDH wild-type and non-1p/19q codeletion." (PMID 38587786, 2025). "Our study showed that high expression of NCAPH corresponded to worse pathophysiological features of gliomas, such as higher WHO grade, IDH wild-type, and non-codeletion of 1p/19q." (PMID 38587786, 2025). "However, there has been no comprehensive analysis of the correlation between NCAPH and PI3K/AKT signaling in glioma cells." (PMID 38587786, 2025).
low grade glioma (2 papers, 2025). A grade I or grade II glioma arising from the central nervous system. "However, the function and pathogenesis of NCAPH in low-grade gliomas (LGG) have been poorly studied, so this study will systematically investigate the effect of NCAPH on LGG and its potential as a target for advancing the diagnosis and treatment of LGG." (PMID 41210692, 2025). "However, the role of NCAPH in low-grade glioma (LGG) has been largely unexplored." (PMID 41210692, 2025).
lymph node metastasis (2 papers, 2019 to 2020). "Although positive NCAPH expression was significantly associated with lymph node metastasis, its expression correlated with a better patient prognosis." (PMID 33311486, 2020). "Moreover, multivariate analysis lymph node metastasis (p = 0.0014) and NCAPH expression (p = 0.0004) remained independent prognostic factors of poor OSCC prognosis." (PMID 31892156, 2019). "Results showed that the expression of NCAPH was significantly associated with tumor size (p = 0.032), depth of invasion (p = 0.029) and lymph node metastasis (p = 0.041), but not related to patients’ age, FIGO staging, tumor differentiation, or distant metastasis, (all p values > 0.05)." (PMID 33311486, 2020).
mesothelioma (2 papers, 2023 to 2025). A usually malignant and aggressive neoplasm of the mesothelium which is often associated with exposure to asbestos. "In addition, we observed that in certain tumors, such as adrenocortical carcinoma and mesothelioma, ERFE was positively co-expressed with the NCAPH and KIF23 genes, which facilitate the separation of chromosomes and cytokinesis during mitosis, thereby promoting tumor cell proliferation." (PMID 36675239, 2023).
microcephaly (2 papers, 2019 to 2022). A congenital or acquired developmental disorder in which the circumference of the head is smaller than normal for the person's age and sex. "For example, biallelic mutations in NCAPD2, NCAPH, and NCAPD3 cause microcephaly." (PMID 36169232, 2022).
bladder urothelial carcinoma (1 paper, 2020). "The results in GEPIA database showed that the expression of NCAPH was significantly higher in esophageal carcinoma, breast invasive adenocarcinoma, head and neck squamous cell carcinoma, and bladder urothelial carcinoma than that in normal tissues." (PMID 33311486, 2020).
bone cancer (1 paper, 2025). A primary or metastatic malignant neoplasm affecting the bone or articular cartilage. "Moreover, analysis of the HPA database revealed that NCAPH was predominantly expressed at high levels in lymphoma, leukemia, and bone cancer, while its expression in brain tumors was moderate." (PMID 41210692, 2025). "Furthermore, NCAPH expression was found to be highest in lymphoma, leukemia, and bone tumor cells, followed by brain tumor cells." (PMID 41210692, 2025).
brain tumor (1 paper, 2025). "Our study shows that NCAPH is low expressed in normal brain tissue and high expressed in brain tumors, especially LGG, and that NCAPH may be a potential risk factor in LGG patients." (PMID 41210692, 2025). "Here, this study attempts to reveal the expression level and single-cell subtype abundance of NCAPH in normal human tissues, pan-cancer, brain tumor cells, brain tumor tissues, and LGG, thereby suggesting the potential effect of NCAPH on LGG." (PMID 41210692, 2025).
breast adenocarcinoma (1 paper, 2024). "Infiltrating ductal carcinomas generated by NCAPH overexpression had a range of histopathological features, including breast adenocarcinomas with papillary differentiation, squamous differentiation, or a mesenchymal pattern." (PMID 38344872, 2024).
cervical adenocarcinoma (1 paper, 2020). An adenocarcinoma arising from the cervical epithelium. "Moreover, NCAPH was undetectable in 52 cases of normal cervical columnar epithelium and 40 cases of cervical adenocarcinoma (data not shown)." (PMID 33311486, 2020).
cholera (1 paper, 2022). "The region with the strongest signal of selection, located on chromosome 2 and encompassing five genes (NRNP200, CIAO1, ITPRIPL1, NCAPH, and TMEM127) was also the region showing the strongest association with cholera, with the top associated SNPs located between the genes NRNP200 and ITPRIPL1." (PMID 35925921, 2022).
fibrosarcoma (1 paper, 2023). A malignant mesenchymal fibroblastic neoplasm affecting the soft tissue and bone. "NCAPH was upregulated in Malignant Fibrous Histiocytoma and Fibrosarcoma with fold changes of 11.886 (p = 5.22E-6) and 10.772 (p = 7.72E-5)." (PMID 37192046, 2023).
gastric cancer (1 paper, 2025). A primary or metastatic malignant neoplasm involving the stomach. "Investigations have showed that high levels of NCAPH can stimulate the proliferation and dissemination of gastric cancer cells through the modulation of DNA damage response, thereby influencing the advancement of gastric cancer." (PMID 41210692, 2025).
invasive ductal breast carcinoma (1 paper, 2024). The most common type of invasive breast carcinoma, accounting for approximately 70% of breast carcinomas. "Therefore, the ErbB2 oncogene appears to reprogram tumour differentiation so that instead of the histopathologically distinct tumours induced by NCAPH overexpression, the characteristics of infiltrating ductal adenocarcinoma predominated." (PMID 38344872, 2024).
Obesity (1 paper, 2026). Accumulation of substantial excess body fat. "Receiver operating characteristic curves manifested that the efficacy of NCAPH and IRS2 in distinguishing between disease (obesity/NAFLD) and normal samples was all excellent." (PMID 42137875, 2026). "Subsequently, based on the results of LASSO and SVM-RFE, we gained two shared biomarkers (NCAPH and IRS2) in obesity and NAFLD, and IRS2 was down-regulated and NCAPH was up-regulated in disease (obesity/NAFLD) samples." (PMID 42137875, 2026).
oral cancer (1 paper, 2019). "NCAPH may induce MDR in oral cancer cells by modulating exosome formation." (PMID 31892156, 2019).
Primary microcephaly (1 paper, 2022). Head circumference below 2 standard deviations below the mean for age and gender at birth. "In addition, also mutations in genes encoding condensin I and II complex members are associated with primary microcephaly, e.g., NCAPD2, NCAPH, NCAPG2 or NCAPD3, which showed altered expression levels in our data as well." (PMID 35099000, 2022).
prostate tumor (1 paper, 2025). "Consistent with the IHC results, NCAPH levels were higher in prostate tumor tissues than in adjacent tissues." (PMID 39991770, 2025).
sarcoma (1 paper, 2023). A usually aggressive malignant neoplasm of the soft tissue or bone. "With Kaplan-Meier Plotter, we verified the prognostic value of NCAPH in sarcoma: the high expression of NCAPH was negatively correlated with OS and RFS, and NCAPH can be used as a promising potential biomarker for sarcoma." (PMID 37192046, 2023). "GEPIA database showed that high expression of NCAPD2, NCAPH, NCAPG and NCAPG2 had a significant correlation with poor overall survival of sarcoma patients (P < 0.05)." (PMID 37192046, 2023). "Six members of the NCAPs family, including NCAPD2, NCAPG, NCAPH, NCAPD3, NCAPG2, and NCAPH2, have been found in different types of sarcomas." (PMID 37192046, 2023). "The high expression of NCAPD2, NCAPG, NCAPH, NCAPD3, and NCAPH2 were all correlated with the relapse-free survival of sarcoma patients, HR = 2.76 (p = 3.3e-05), 2.72 (p = 0.0012), 2.71 (p = 0.0026), 1.87 (p = 0.01) and 2.08 (p = 0.029) respectively." (PMID 37192046, 2023). "By evaluating NCAPs in normal and sarcoma tissues using the GEPIA database, we noticed significantly higher expression patterns of NCAPD2, NCAPG, NCAPH, NCAPG2, and in sarcoma samples compared to normal tissues." (PMID 37192046, 2023). "In this study, ONCOMINE, GEPIA, Kaplan-Meier plotter, DAVID (KEGG and GO analysis), and TIMER datasets were utilized to study the high expression, prognosis analysis, signal pathway and immune correlation of NCAPD2, NCAPG, NCAPH, NCAPD3, NCAPG2, and NCAPH2 in sarcoma for the first time." (PMID 37192046, 2023). "In the Kaplan-Meier Plotter database, high expression of NCAPD2, NCAPG, NCAPH, and NCAPD3 was correlated with poor overall survival in sarcoma patients (p < 0.05), HR = 2.23 (p = 0.00016), 1.63 (p = 0.015), 1.83 (p = 0.0025), and 1.63 (p = 0.024), respectively." (PMID 37192046, 2023). "Up to now, NCAPD2, NCAPG, NCAPH, NCAPD3, NCAPG2, and NCAPH2 have not been mentioned in sarcoma, except NCAPG mentioned in Ewing sarcoma." (PMID 37192046, 2023).
squamous intraepithelial lesion (1 paper, 2020). "NCAPH was overexpressed in 12.2% of normal cervical squamous epithelium (10/82), 14.7% of high-grade squamous intraepithelial lesion (HSIL) (5/34) and 40.6% of ICSCC (67/165)." (PMID 33311486, 2020).